CSF2 (colony stimulating factor 2)
Diseases named in the same sentence as CSF2 in open-access papers (continued):
Sharing a sentence is not in itself a finding about the gene and the disease.
renal fibrosis (5 papers, 2021 to 2024). A final common manifestation of a wide variety of chronic kidney diseases characterized by glomerulosclerosis and tubulointerstitial fibrosis. "At the same time, expression of inflammatory cytokines (Il1b, Csf2, Tnfa, and Cxcl10), renal fibrosis, and profibrotic genes (Col1a1, Col3a1, Fn1, and Vim) was lower in the FA-treated Casp9 HZ mice." (PMID 34739325, 2021). "Several previously reported protective genes (hypoxia inducible factor 1, HIF-1α; heme oxygenase 1; HO-1, colony-stimulating factor 2, CSF-2; bone morphogenetic protein-7, BMP-7; and activin-like kinase 3; ALK3) against renal fibrosis progression after ischemia reperfusion were evaluated after IR." (PMID 34302012, 2021).
schizophrenia (5 papers, 2009 to 2023). A major psychotic disorder characterized by abnormalities in the perception or expression of reality. "Collectively, these studies support a role for the IL3/CSF2 pathway in schizophrenia." (PMID 19721717, 2009).
acne (4 papers, 2014 to 2022). An inflammatory process of the sebaceous glands which is characterized by comedones, nodules, papules and/or pustules on the skin. "Furthermore, Th17 cell products IL-17A, IL-22, IL-26, TNF and IL-17 induced chemokines CSF2 and CCL20 were also expressed at higher levels in acne lesions." (PMID 25153527, 2014). "The expression of cytokines IL-6, IL-12p40, INF-γ and TGF-β have not been studied earlier in acne lesions as also noticed by Thiboutot and co-workers, nor cytokines IL-17A, IL-17F, IL-23p19, IL-22 and chemokines CCL20 and CSF2." (PMID 25153527, 2014).
airway hyperresponsiveness (4 papers, 2009 to 2023). "Of those dysregulated genes, four were associated with immune-mediated inflammatory diseases (Csf2; Crlf2; Rnase2b; Tpsb2) and one with airway hyperresponsiveness (Prg2), while Il-13 was associated with both of those pathways." (PMID 36834405, 2023).
aspergillosis (4 papers, 2018 to 2024). Aspergillosis is an infection, growth, or allergic response caused by the Aspergillus fungus. "CSF2 is crucial for the recruitment of monocytes and is involved in the neutrophil and monocyte antifungal activity against A. fumigatus in mice model of aspergillosis." (PMID 34983375, 2022).
leprosy (4 papers, 2021 to 2025). Leprosy is a chronic infectious disease affecting primarily the skin and peripheral nervous system. "A qPCR performed to evaluate pro- and anti-inflammatory related gene expression in skin lesions of leprosy patients revealed that pro-inflammatory genes STAT1, TNF, IFNG, IL15 and CSF2 are increased in PB cells, whereas anti-inflammatory MSR1 and PPARG genes are increased in MB cells." (PMID 34354699, 2021).
prostate (4 papers, 2020 to 2025). "In this study, we demonstrate that bladder ILC2 cells express Csf2 that was known to modulate macrophage activity and chronic prostatitis/chronic pelvic pain syndrome." (PMID 40100274, 2025).
urothelial carcinoma (4 papers, 2011 to 2021). A malignant neoplasm derived from the transitional epithelium of the urinary tract (urinary bladder, ureter, urethra, or renal pelvis). "Overexpression of CSF2 was demonstrated to be implicated with advanced tumor status and poor prognosis in urothelial carcinoma and involved in several cancer-related pathways." (PMID 31894857, 2020). "Additionally, it had been shown that adverse clinical outcomes were caused through overexpression of CSF2 in urothelial carcinoma and epithelial carcinoma of the bladder." (PMID 33748185, 2021).
uveal melanoma (4 papers, 2014 to 2025). A melanoma derived from melanocytes of the uveal tract. "In metastases of uveal melanomas, several proteins were found to be upregulated: Colony stimulating factor 2, Ficolin precursor, Haptoglobin -2 precursor, Hemopexin precursor, α-1-antitrypsin precursor, α-1-antichymotrypsin precursor, Vitronectin precursor, and Down syndrome cell adhesion molecule." (PMID 24392146, 2014).
acute pyelonephritis (3 papers, 2020 to 2025). "Csf2 was initially characterized as a cytokine that facilitates the differentiation of granulocytes and macrophages from bone marrow precursors and plays a pivotal role in UPEC-induced acute pyelonephritis." (PMID 40100274, 2025).
astrocytoma (3 papers, 2011 to 2021). "Additionally, protein levels of colony-stimulating factor 2, while not detectable in normal brain, were abundant in high-grade astrocytoma (8.2 ± 3; **P < .01)." (PMID 34131649, 2021).
clear-cell renal cell carcinoma (3 papers, 2016 to 2024). "Taken together, these observations unveil the oncogenic properties associated with csf2, elucidating its pivotal role in preventing the proliferation, invasion, and migration of renal clear cell carcinoma." (PMID 39011666, 2024). "In conclusion, these findings reveal that csf2 inhibit the growth, infiltration and movement of cells associated with renal clear cell carcinoma." (PMID 39011666, 2024). "Indeed, experimental results showing that CSF2 inhibits the growth, infiltration, and movement of renal clear cell carcinoma‐associated cells may reflect its complex role in regulating immune responses and the tumour microenvironment." (PMID 39011666, 2024). "Therefore, further studies are needed to explain this contradiction and to better understand the mechanism of CSF2's role in renal clear cell carcinoma." (PMID 39011666, 2024). "Analysis of The Cancer Genome Atlas (TCGA) kidney clear cell carcinoma (KIRC) database for RNA sequencing data related to ccRCC showed significantly reduced overall survival in high expressers of CXCL8 (IL8), CCL5, CSF2, TFPI-2, and SERPINE1 (PAI1)." (PMID 35886951, 2022).
ischemic stroke (3 papers, 2023 to 2025). A stroke disorder caused by obstruction of blood flow to the brain, due to thrombotic (local blood clot formation) or embolic (due to a blood clot or other material traveling from another site) event. "Twelve genes have been reported as potential regulators of HT in ischemic stroke in previous studies: Casp3, Csf2, Ctnnb1, Cxcl12, Hif1a, Il1b, Mtor, Ptgs2, Ptprc, Tlr2, Tlr4, and Vcam1." (PMID 40002863, 2025).
meningitis (3 papers, 2021 to 2025). A disorder characterized by acute inflammation of the meninges of the brain and/or spinal cord. "Other cytokines known to be upregulated in the CSF during meningitis are CSF2 (GM-CSF), CCL2 (MCP-1), CCL4 (MIP-1β)." (PMID 34863201, 2021).
metabolic syndrome (3 papers, 2011 to 2023). A cluster of metabolic risk factors for CARDIOVASCULAR DISEASES and TYPE 2 DIABETES MELLITUS. "Contrarily, the s-CSF2-Ab levels were inversely associated with dyslipidemia (P = 0.027) possibly because the patients but not the HDs were taking cholesterol-lowering drugs, such as statins." (PMID 36844744, 2023).
synovitis (3 papers, 2015 to 2020). Inflammation of a synovial membrane. "The levels of plasma epidermal growth factor (EGF), colony stimulating factor 2 (CSF2), interleukin 4/13 (IL4/13), fibroblast growth factor 2 (FGF2) and MIP-1 α were significantly lower in patients with a joint bleeding compared to patients without a bleeding or synovitis." (PMID 33023246, 2020).
trachoma (3 papers, 2009 to 2023). "Risk effects estimated by OR (95%CI) for the association between extended and reduced haplotypes across IL3 and CSF2 and risk of scarring trachoma and trichiasis." (PMID 20015396, 2009). "They contain the genes interleukin 8 (IL8) and granulocyte-macrophage colony stimulatory factor (CSF2) which have strong candidacy to affect risk of the scarring complications of trachoma." (PMID 20015396, 2009). "We report here an analysis of the risk effects at IL8 and CSF2, in a Gambian case-control association study of scarring trachoma and trichiasis, which took the LD structure at these loci into account." (PMID 20015396, 2009). "For example, poor facial cleanliness and presence of flies are risk factors for active trachoma, while genetic polymorphisms in TNF-α, IFNγ, IL-10, IL8, and CSF2 have been linked to risk of trachomatous scarring." (PMID 37287960, 2023). "No SNP(PEMMAX < 0.01) was detected in any of thegenes IL8, IL10, CSF2, IFNG, HP, CCL8 or MMP9; all of which had beenpreviously reported to associate with trachoma." (PMID 26616738, 2015). "Proportions of cases and controls with different SNP-genotypes at the CSF2 locus and risk estimates from conditional logistic regression (CLR) analysis of 651 matched case-control pairs for each SNP for scarring trachoma." (PMID 20015396, 2009).
adenovirus infection (2 papers, 2019 to 2021). "As a result, Csf2-/- mice show increased susceptibility to a variety of pulmonary and systemic infections including streptococcal, Pseudomonas aeruginosa, Pneumocystis carinii, malaria, and adenovirus infections." (PMID 34880857, 2021).
bone fracture (2 papers, 2016 to 2017). "A PPI network was constructed with 167 nodes and 233 edges, and module analysis demonstrated that CCL2, CSF2, NOS2, and DLC1 may stimulate bone overgrowth after femoral fracture via anti-apoptosis-related functions." (PMID 28095896, 2017).
enthesitis (2 papers, 2020 to 2025). Inflammation at the site of insertion of ligaments, tendons, and other fibrous structures into bone. "Other key genes involved in enthesitis were up‐regulated including CSF2 (encoding granulocyte–macrophage CSF), IL12B, IL6, and notably CD80 and CD83 encoding the M1‐associated costimulatory receptors." (PMID 40320905, 2025).
glomerulonephritis (2 papers, 2023). A renal disorder characterized by damage in the glomeruli. "We also examined the s-CSF2-Ab and s-CSF2pep-Ab levels in the sera of 82 HDs and 300 patients with CKD, including 145 patients with diabetic kidney disease (CKD type 1), 32 patients with nephrosclerosis (CKD type 2), and 123 patients with glomerulonephritis (CKD type 3)." (PMID 36844744, 2023).
kidney injury (2 papers, 2020). Trauma to the kidney. "Csf2 blockade through antibodies strongly inhibited M1 macrophage differentiation and increased mortality in CLP-induced septic kidney injury." (PMID 32733471, 2020).
myxofibrosarcoma (2 papers, 2023). A malignant fibroblastic neoplasm arising from the soft tissue. "Upon nuclear entry together with STAT5B, PAK1 co-transactivated the pro-angiogenic CSF2 gene, encoding granulocyte-macrophage colony stimulating factor 2 (a.k.a GM-CSF), to increase CSF2 expression, hence enhancing angiogenesis in myxofibrosarcomas." (PMID 37564209, 2023). "PAK1 amplification has been associated with advanced tumour stages, higher MVD, and notable colony stimulating factor 2 expression (CSF2) in myxofibrosarcoma." (PMID 38067120, 2023). "In vitro, genetic ablations of PAK1 and CSF2, the CSF2-directed antibody, and pharmacological intervention with PF-3758309 inhibitor all significantly abrogated angiogenesis of myxofibrosarcoma." (PMID 37564209, 2023). "Our in vitro evidence indicated that CSF2 is a potential PAK1-driven angiogenic factor self-produced by myxofibrosarcoma cells (Figure-2)." (PMID 37564209, 2023). "Our findings provide not only prognostic insight into future risk stratification but also a novel biomarker-guided therapeutic approach to targeting angiogenesis in aggressive myxofibrosarcomas which harbor the vulnerable PAK1/STAT5B/CSF2 proangiogenic axis." (PMID 37564209, 2023). "These clues further infer a question of whether, in a positive feedback loop, overproduced CSF2 in myxofibrosarcoma cells depends on nuclear PAK1 to invigorate the activity of JAK2/STAT5B cascade." (PMID 37564209, 2023). "Conclusively, the nuclear entry of overexpressed/activated PAK1 endows myxofibrosarcomas with pro-angiogenic function, highlighting the vulnerable PAK1/STAT5B/CSF2 regulatory axis." (PMID 37564209, 2023). "Myxofibrosarcoma specimens were analyzed for the levels of PAK1, phospho-PAKT423, CSF2 and microvascular density (MVD) and those of PAK1 gene and mRNA." (PMID 37564209, 2023). "Using TMA-assembled primary myxofibrosarcoma tissues, we validated the clinical relevance of the PAK1 gene copy number, PAK1 mRNA abundance, and immunoexpression levels of whole-cell PAK1, whole-cell and nuclear p-PAK1T423, and cytoplasmic CSF2." (PMID 37564209, 2023).
chondrosarcoma (1 paper, 2014). A malignant cartilaginous matrix-producing mesenchymal neoplasm arising from the bone and soft tissue. "About CSF2, which was the most up-regulated gene by IL-1β, no reports on chondrosarcomas have been published to our knowledge so far." (PMID 24901233, 2014).
dermatophytosis (1 paper, 2022). A common fungal infection of the stratum corneum of the skin, hair, or nails by a dermatophyte. "Thus, our results provide new insights into the modulation profile of CSF2 and GM-CSF secretion by human keratinocytes in an infection-like scenario using the main global causative agent of dermatophytosis." (PMID 36354918, 2022).
kidney transplant (1 paper, 2024). A surgical procedure in which one or both kidneys from a donor are implanted into a recipient. "Additionally, tacrolimus significantly inhibits cytokines regulated by NFAT, such as IL-2, IFN-γ, and colony-stimulating factor 2 (CSF2) in post-kidney transplant patients." (PMID 38774214, 2024).
melasma (1 paper, 2022). "TheWNT3A, EDN3, ESR2, PTG2, MMP1, and SOD2 genes were up-regulated, whereas the COL4A1, CSF2, DKK3, COL7A1, TIMP4, CCL2, and CDH11 genes were down-regulated in melasma skin fibroblasts when compared to the ones from adjacent healthy skin." (PMID 35840442, 2022).
nephrosclerosis (1 paper, 2023). Hardening of the kidney due to infiltration by fibrous connective tissue (fibrosis), usually caused by renovascular diseases or chronic hypertension. "Patients with diabetic CKD (CKD type 1) and those with nephrosclerosis (CKD type 2) exhibited equally higher s-CSF2-Ab and s-CSF2pep-Ab levels than the HDs." (PMID 36844744, 2023).
penile cancer (1 paper, 2020). A primary or metastatic malignant neoplasm that affects the penis. "IPA identified potential upstream regulators that explain the transcriptional changes of human penile cancer, which included activated targets by pro-inflammatory factors such as TNF, CSF2, IFNγ, IL1B, and inhibited targets by TGFβ1." (PMID 32358507, 2020).
pregnancy disorder (1 paper, 2021). A disorder that is related to pregnancy. "A multiple-SNP analysis showed that the TT variants for CSF2 and FLT1 polymorphisms correlated with an approximately two-fold increase in the PROM risk when corrected for APTT, PLT parameters and pregnancy disorders (p ≤ 0.050)." (PMID 34828331, 2021). "Among the double-SNP variants, the TT complex genotypes for CSF2 rs25881 and FLT1 rs722503 polymorphisms correlated with an increased risk of PROM and pPROM, after adjusting for APTT, PLT parameters or pregnancy disorders." (PMID 34828331, 2021). "We found in our study that genetic changes, localized in SNPs from CSF2, FLT1, TFPI and TLR9 genes, were associated with PROM, when the results had been adjusted for APTT, PLT parameters or pregnancy disorders." (PMID 34828331, 2021). "Similarly, the TT double-SNP variants for the CSF2 and FLT1 polymorphisms had an approximately two-fold increased risk of PROM when the results were adjusted for DM and other pregnancy disorders." (PMID 34828331, 2021). "An additional comparison between the pPROM and tPROM cases showed that the C alleles for the CSF2, FLT1 and TFPI polymorphisms, and the T allele for the TLR9 SNP in different complex variants, were more common in the women with pPROM after adjusting for APTT, PLT parameters and pregnancy disorders." (PMID 34828331, 2021).
pterygium (1 paper, 2011). A wedge-shaped fibrovascular lesion arising from the bulbar conjunctiva and extending to the cornea. "This raises the possibility that critical DNA demethylation may facilitate transcription factor(s) downstream of CSF2 to bind to regulatory sequences of CD24 and MMP-2, with a consequential increase in Wnt/β-catenin signaling, which has been previously reported in pterygium." (PMID 21359202, 2011).
Trichiasis (1 paper, 2009). Inversion and rubbing of the eyelashes against the globe of the eye. "MMP9 Q279R AG heterozygotes were most protected from risk of trichiasis when this genotype was combined with the CSF2_27348 TT genotype (OR, (95%CI) = 0.41 (0.25, 0.66)." (PMID 20015396, 2009).